ANP32B (acidic nuclear phosphoprotein 32 family member B)
Description:
Multifunctional protein that is involved in the regulation of many processes including cell proliferation, apoptosis, cell cycle progression or transcription. Regulates the proliferation of neuronal stem cells, differentiation of leukemic cells and progression from G1 to S phase of the cell cycle. As negative regulator of caspase-3-dependent apoptosis, may act as an antagonist of ANP32A in regulating tissue homeostasis. Exhibits histone chaperone properties, able to recruit histones to certain promoters, thus regulating the transcription of specific genes. Also plays an essential role in the nucleocytoplasmic transport of specific mRNAs via the uncommon nuclear mRNA export receptor XPO1/CRM1. Participates in the regulation of adequate adaptive immune responses by acting on mRNA expression and cell proliferation (By similarity). (Microbial infection) Plays an essential role in influenza A and B viral genome replication. Also plays a role in foamy virus mRNA export from the nucleus to the cytoplasm.
Synonyms: PHAPI2; APRIL; SSP29
Tractability: PROTAC: ubiquitination databases record sites on it; its protein half-life has been measured.
Gene: Protein-coding gene on chromosome 9 (97,983,215 to 98,015,943, forward strand). Ensembl gene ENSG00000136938.
Subcellular location: Nucleus (Isoform 1); Cytoplasm; Cytoplasm (Isoform 2)
Subcellular location (Human Protein Atlas): Nucleoplasm; Centrosome; Cytosol
Gene Ontology:
Molecular function: histone binding; protein binding; RNA polymerase binding
Biological process: negative regulation of apoptotic process; negative regulation of cell differentiation; positive regulation of protein export from nucleus; regulation of apoptotic process
Cellular component: cytoplasm; cytosol; extracellular exosome; nucleolus; nucleoplasm; nucleus
Genetic constraint (gnomAD): Loss-of-function variants: 5 observed, 28.9 expected, observed/expected ratio (o/e) 0.17, 90% interval 0.089 to 0.36. The upper end of that interval is the gene's LOEUF score, 0.36, which puts it in group 1 of 6, group 1 being the genes least tolerant of losing a copy. Missense variants: 162 observed, 244.1 expected, observed/expected ratio (o/e) 0.66, 90% interval 0.58 to 0.76. Synonymous variants: 86 observed, 92.79 expected, observed/expected ratio (o/e) 0.93, 90% interval 0.78 to 1.11.
Homologues: Orthologues: chimpanzee ANP32B (99% identical), macaque ANP32B (94% identical), rabbit ANP32B (88% identical), guinea pig ANP32B (87% identical), mouse Anp32b (87% identical), pig ANP32B (86% identical), dog ANP32B (84% identical), rat Anp32b (83% identical), tropical clawed frog anp32b (81% identical), zebrafish anp32b (79% identical), Drosophila melanogaster Mapmodulin (49% identical), Caenorhabditis elegans F33H2.3 (35% identical), and 1 more. Paralogues in human: ANP32A (71% identical), ANP32E (61% identical), ANP32D (37% identical).
Diseases named in the same sentence as ANP32B in open-access papers:
ANP32B is named in the same sentence as 27 diseases in open-access papers, as found by Europe PMC text mining. Sharing a sentence is not in itself a finding about the gene and the disease. The quoted sentences say what the papers report.
breast carcinoma (8 papers, 2016 to 2025). "Taken together, these data suggest that ANP32B may be closely associated with the proliferation of breast cancer cell lines." (PMID 26844697, 2016). "All these data strongly suggested that specific loss of ANP32B could significantly inhibit breast cancer growth in vivo." (PMID 26844697, 2016). "Higher ANP32B mRNA expression is a marker of poor prognosis in patients with breast cancer, whereas ANP32B was found to suppress breast cancer tumor growth." (PMID 38192816, 2024). "ANP32B downregulation has been shown to exert anti-apoptotic effects on hepatocellular carcinoma and breast cancer cells." (PMID 36674590, 2023). "A study on breast cancer showed that ANP32B is necessary not only for the normal development of the body but also for the growth of breast cancer cells." (PMID 35280441, 2022). "Collectively, our findings suggest that ANP32B is an oncogene and a potential therapeutic target for breast cancer treatment." (PMID 26844697, 2016). "Considering that some physiological and pathological processes share many common molecular regulators, and ANP32B mRNA expression is a marker for aggressive breast cancer, we proposed that ANP32B also functions in breast cancer." (PMID 26844697, 2016). "Clinical data set analyses showed that ANP32B protein level is highly expressed in breast cancer patients and the elevated ANP32B protein expression is directly related with histological grade of breast cancer tissues." (PMID 26844697, 2016). "There was also a report that Anp32b expression was related to worse outcome in patients with breast cancer." (PMID 27699085, 2016). "In line with this, ANP32B protein has higher expression in malignant tissues than adjacent normal tissues from a cohort of breast cancer patients, and its expression level positively correlates with their histopathological grades." (PMID 26844697, 2016). "ANP32B was shown to be important for cell proliferation, apoptosis, and cell cycle progression, and to participate in various types of cancer, including leukemia, breast cancer, hepatocellular carcinoma, pancreatic adenocarcinoma and thyroid carcinoma." (PMID 38192816, 2024). "According to a study on ANP32B in mouse model, a high expression of this gene may promote the progression of breast cancer." (PMID 31480430, 2019). "Then, we examined the effect of ANP32B knockdown on breast cancer cell proliferation." (PMID 26844697, 2016). "Notably, ANP32B has been highly detected in breast cancer patients, thus highlighting ANP32B as a potential therapeutic target for breast cancer treatment." (PMID 26844697, 2016). "Moreover, an increase of ANP32B protein level in tumor tissues over adjacent normal tissues was also confirmed by western blot analysis in five paired clinical breast cancer specimens." (PMID 26844697, 2016). "ANP32B silencing by RNAi also inhibited breast cancer cell proliferation in vitro and in vivo." (PMID 26844697, 2016). "We further investigated whether ANP32B regulates cancer cell proliferation with breast cancer cells as models." (PMID 26844697, 2016). "The present results suggest that ANP32B expression in breast cancer may differ from that in HCC." (PMID 28486557, 2017). "It has been reported that ANP32B expression, which is positively correlated with phosphorylated Akt levels, regulates AKT activation in breast cancer." (PMID 28486557, 2017). "Furthermore, the restoration of AKT or constitutively active AKT expression could rescue the inhibition of cell proliferation by ANP32B deficiency, suggesting the inhibition of cell proliferation by ANP32B deficiency is primarily mediated through AKT activation in breast cancer cells." (PMID 26844697, 2016). "For this purpose, we used two pairs of shRNAs (sh32b#1 and sh32b#2) specifically against ANP32B to generate stable ANP32B knockdown along with a control shRNA transfectant (shNC) in BT549, MCF7 and MDA-231-D3H2LN breast cancer cell lines." (PMID 26844697, 2016).
breast carcinoma (continued). "We detected ANP32B and p-AKT expression by IHC staining in tumor tissues from breast cancer patients." (PMID 26844697, 2016). "Indeed, DDR1i caused differential expression in several direct RUNX1 target genes including DUT, an essential nucleotide metabolism enzyme seen upregulated across breast cancers, and MYC, along with ANP32B, PLEC, CEBPD, ID1, and STAT3." (PMID 40614729, 2025). "Patients with high expression of ANP32B and ANP32E had poor prognosis in breast cancer." (PMID 35280441, 2022). "Another study in 2016 reported that not all breast cancer subtypes can be induced by the abnormal methylation or expression of our predicted gene ANP32B, thereby indicating the conditional methylation status of this gene contributes to different breast cancer subtypes." (PMID 31480430, 2019). "These two specific shRNAs could effectively knockdown ANP32B but not its closely related ANP32A expression in these breast cancer cell lines." (PMID 26844697, 2016).
virus infection (7 papers, 2014 to 2024). "The proteins co-localize in the nucleus both in recombinant context and in viral infection, and ANP32B copurifies with M in cells expressing both." (PMID 37376602, 2023). "MA plot analyses reveal a shift towards a downregulated gene expression profile in ANP32B−/− mice during virus infection, compared to ANP32B+/+ mice." (PMID 32231671, 2020). "In addition, involvement of ANP32B in viral infection, acting either as a critical cellular cofactor or as restriction factor, has been reported for various viruses." (PMID 30890743, 2019). "ANP32B may serve as a binding factor, either involved in the regulation of nucleo-cytoplasmic trafficking of henipavirus M proteins or in the targeted interference of henipavirus M proteins with cellular reactions to virus infections." (PMID 24823948, 2014). "Our screen demonstrated that RNAi-mediated silencing of ANP32B increases (but not significantly) virus infection (Z score 1.54), suggesting that ANP32B may have a hitherto undescribed antiviral role." (PMID 27010548, 2016).
influenza (5 papers, 2019 to 2024). An acute viral infection of the respiratory tract, occurring in isolated cases, in epidemics, or in pandemics; it is caused by serologically different strains of viruses (influenzaviruses) designated A, B, and C, has a 3-day incubation period, and usually lasts for 3 to 10 days. "We next tested the ability of ANP32A and ANP32B proteins from different mammalian species relevant to influenza ecology to support influenza A polymerase activity." (PMID 37074204, 2023). "In conclusion, the transcriptional landscape of the IAV infected murine lung strongly suggests that ANP32B plays a crucial role in the regulation of pro-inflammatory gene expression that ultimately dictates influenza disease outcome in mice." (PMID 32231671, 2020). "Overall, a distinct transcriptional profile characterized by a global reduction of antiviral gene expression was identified that distinguishes the ANP32B−/− mice from their ANP32B+/+ litter mates during influenza infection." (PMID 32231671, 2020). "ANP32A and ANP32B have been previously identified binding with viral polymerase and promoting human influenza viral vRNA synthesis." (PMID 30996088, 2019). "Targeting ANP32B or its regulated pathways might therefore pose a new strategy to combat severe influenza." (PMID 32231671, 2020). "Human ANP32A and ANP32B contribute equally to support human influenza viral RNA replication." (PMID 30996088, 2019). "ANP32A is the only ANP32 family member that efficiently supports influenza polymerase in birds, while in humans and most other mammalian influenza hosts ANP32A and ANP32B can both support polymerase activity to varying levels." (PMID 37074204, 2023). "We observed similar results from the reconstitution of ANP32B or both ANP32A and ANP32B, indicating that huANP32A&B are key factors in triggering the replication of the human influenza viral genome." (PMID 30996088, 2019). "Additionally, genes involved in cell processes and cytoskeletal structural elements were upregulated in activated cTfh cells compared to resting cells following influenza vaccination: ELMO2, ACTG1, STMN1, ANP32B, UCP2, and HMGB3." (PMID 37063867, 2023). "Our findings in ANP32B+/+ and ANP32B−/− mice on the other hand suggest that ANP32B is required for the induction of a subset of pro-inflammatory cytokine responses (TNF-α, MCP-1, IL-1β, and IL-6), upon influenza infection in the murine lung." (PMID 32231671, 2020).
hepatocellular carcinoma (3 papers, 2017 to 2024). A malignant tumor that arises from hepatocytes. "ANP32B mRNA and protein are highly expressed in hepatocellular carcinoma (HCC), with these levels of expression associated with tumor cell proliferation and invasion, suggesting that ANP32B is pro-oncogenic in HCC." (PMID 38192816, 2024).
leukemia (3 papers, 2022 to 2024). A malignant (clonal) hematologic disorder, involving hematopoietic stem cells and characterized by the presence of primitive or atypical myeloid or lymphoid cells in the bone marrow and the blood. "While there have been no direct reports on the regulation of histone modification by ANP32B, its counterpart ANP32A, another member of the ANP32 protein family, has been implicated in the regulation of histone acetylation in leukemia pathogenesis." (PMID 38383388, 2024). "In contrast, however, ANP32B has been reported to activate caspase-3 to promote the apoptosis of leukemia cells." (PMID 38192816, 2024). "The findings imply that ANP32B potentially plays a multifaceted role in leukemia." (PMID 38383388, 2024). "Additionally, we conducted western blotting analysis to evaluate the expression levels of ANP32B in leukemia cell lines." (PMID 38383388, 2024). "In acute leukemia, ANP32B can promote the apoptosis of leukemia cells by activating caspase-3." (PMID 35280441, 2022). "Additionally, ANP32B has been found to diminish the differentiation ability of leukemia cells." (PMID 38383388, 2024). "Notably, previous studies have reported on the role of ANP32B in CML and ALL, suggesting its general significance in leukemia." (PMID 38383388, 2024).
Stroke (2 papers, 2016 to 2022). Sudden impairment of blood flow to a part of the brain due to occlusion or rupture of an artery to the brain. "For example, the molecular target of hsa-miR-676-3p, SMURF2, is involved in neurodifferentiation in recovery phase following ischemic stroke, while its other targets, PTPRB and ANP32B, have also been previously investigated in experimental stroke models." (PMID 35328807, 2022). "Grb2, Acot11, Acat2, Scp2, Anp32b and Ppp2r5d were down-regulated after stroke." (PMID 27699085, 2016).
acute lymphoblastic leukemia (1 paper, 2024). Leukemia with an acute onset, characterized by the presence of lymphoblasts in the bone marrow and the peripheral blood. "However, recent study suggests that ANP32B exerts a suppressive effect on B-cell acute lymphoblastic leukemia (ALL) in mice by activating PU." (PMID 38383388, 2024).
acute myeloid leukemia (1 paper, 2024). Acute myeloid leukemia (AML) is a group of neoplasms arising from precursor cells committed to the myeloid cell-line differentiation. "Our study has provided evidence to support the notion that super-enhancer related gene ANP32B plays a significant role in promoting tumor proliferation in acute myeloid leukemia (AML)." (PMID 38383388, 2024). "Consequently, we conducted further investigations to elucidate the manner in which ANP32B regulates C-MYC expression in acute myeloid leukemia cells." (PMID 38383388, 2024).
autoimmune disorders (1 paper, 2019). "Therefore, Anp32b appears to fulfill a role in regulating adequate adaptive immune responses and, hence, may be involved in dysregulation of pathways leading to autoimmune disorders and/or immune deficiencies." (PMID 30890743, 2019). "Taking into account that Th17/Th1 T cells play a crucial role in autoimmunity, and to unravel a possible role of Anp32b in a more complex and inflammatory immunological environment, we next decided to investigate Anp32b KO animals using the experimental autoimmune encephalitis (EAE) model." (PMID 30890743, 2019).
breast tumor (1 paper, 2016). "These in vitro results prompted us to examine whether ANP32B has some effects on breast tumor growth in vivo." (PMID 26844697, 2016).
colorectal cancer (1 paper, 2024). A primary or metastatic malignant neoplasm that affects the colon or rectum. "ANP32B may alter the sensitivity of colorectal cancer cells to PARP1 inhibitor via a mechanism associated with the HPF1 gene." (PMID 38192816, 2024). "ANP32B, a member of the acidic leucine-rich nuclear phosphoprotein 32 family member B, is aberrantly expressed in various cancers, including colorectal cancer." (PMID 38192816, 2024). "ANP32B expression was found to be significantly upregulated in colorectal cancer patient samples and cell lines." (PMID 38192816, 2024). "The present study therefore analyzed the expression of ANP32B and its activity in colorectal cancer patient samples and colorectal cancer cell lines." (PMID 38192816, 2024). "Overexpression of ANP32B also reduced the sensitivity of colorectal cancer cells to PARP1 inhibitor, consistent with the oncogenic role of ANP32B." (PMID 38192816, 2024). "Analysis of colorectal cancer samples from The Cancer Genome Atlas showed that ANP32B and HPF1 expression were positively correlated, and recovery assays showed that ANP32B promoted colorectal cancer progression by up-regulating HPF1." (PMID 38192816, 2024). "Upregulation of ANP32B enhanced colorectal cancer cell proliferation and migration, whereas downregulation of ANP32B suppressed colorectal cancer cell proliferation." (PMID 38192816, 2024). "In summary, these findings showed that ANP32B acted as a tumor promoter, potentiating both colorectal cancer malignancy and drug resistance." (PMID 38192816, 2024). "•ANP32B promotes the progression of colorectal cancer by up-regulating HPF1." (PMID 38192816, 2024). "RNA sequencing analysis of differentially expressed genes in ANP32B silenced colorectal cancer cells showed that histone PARylation factor 1 (HPF1), which protects against DNA damage by interacting with the anti-tumor target PARP1, was significantly downregulated." (PMID 38192816, 2024). "•ANP32B is highly expressed in colorectal cancer patient samples." (PMID 38192816, 2024). "Targeting the ANP32B/HPF1 axis may have benefit for patients with colorectal cancer." (PMID 38192816, 2024). "However, the function and mechanism of action of ANP32B in colorectal cancer remain unclear." (PMID 38192816, 2024).
Duchenne muscular dystrophy (1 paper, 2021). Duchenne muscular dystrophy (DMD) is a neuromuscular disease characterized by rapidly progressive muscle weakness and wasting due to degeneration of skeletal, smooth and cardiac muscle. "Another example of type 1–specific protein is ANP32B, which has been recently reported to be significantly increased in the serum of Duchenne muscular dystrophy patients." (PMID 34727990, 2021).
glioma (1 paper, 2024). A benign or malignant brain and spinal cord tumor that arises from glial cells (astrocytes, oligodendrocytes, ependymal cells). "First, we only explored the effect of ANP32B/HPF1 axis on malignant phenotype of glioma from in vitro experiments, without further verification in vivo." (PMID 38192816, 2024).